IGLV5-52 (immunoglobulin lambda variable 5-52)
Description:
V region of the variable domain of immunoglobulin light chains that participates in the antigen recognition. Immunoglobulins, also known as antibodies, are membrane-bound or secreted glycoproteins produced by B lymphocytes. In the recognition phase of humoral immunity, the membrane-bound immunoglobulins serve as receptors which, upon binding of a specific antigen, trigger the clonal expansion and differentiation of B lymphocytes into immunoglobulins-secreting plasma cells. Secreted immunoglobulins mediate the effector phase of humoral immunity, which results in the elimination of bound antigens. The antigen binding site is formed by the variable domain of one heavy chain, together with that of its associated light chain. Thus, each immunoglobulin has two antigen binding sites with remarkable affinity for a particular antigen. The variable domains are assembled by a process called V-(D)-J rearrangement and can then be subjected to somatic hypermutations which, after exposure to antigen and selection, allow affinity maturation for a particular antigen.
Gene: Immunoglobulin variable (V) gene on chromosome 22 (22,318,727 to 22,319,226, forward strand). Ensembl gene ENSG00000211643.
Subcellular location: Secreted; Cell membrane
Gene Ontology:
Biological process: immune response
Cellular component: extracellular region; immunoglobulin complex; plasma membrane
Homologues: Paralogues in human: IGLV5-37 (75% identical), IGLV5-45 (75% identical), IGLV5-48 (66% identical), IGLV11-55 (63% identical), IGLV4-60 (60% identical), IGLV4-69 (56% identical), IGLV2-18 (51% identical), IGLV1-50 (50% identical), IGLV1-40 (49% identical), IGLV2-11 (49% identical), IGLV2-14 (49% identical), IGLV9-49 (49% identical), and 81 more.